MMP9 (matrix metallopeptidase 9)
Diseases named in the same sentence as MMP9 in open-access papers (continued):
Sharing a sentence is not in itself a finding about the gene and the disease.
periodontitis (continued). "Moreover, during periodontitis, it has been hypothesized that MMP-9, together with CRP, may negatively upregulate nitric oxide (NO), which in turn may adversely affect the endothelium and arterial vascular tone and finally lead to endothelial dysfunction and augmented CVD risk." (PMID 33810003, 2021). "The results of the present study show that patients with CVD and periodontitis + CVD had elevated levels of serum and salivary MMP-9." (PMID 33810003, 2021). "Saliva from the periodontitis subjects had significantly higher mean levels of MMP-8 (p = 0.03) and MMP-9 (p = 0.03) than saliva from the healthy subjects." (PMID 35048079, 2021). "MMP-9 is expressed in adult periodontitis and plays a pivotal role in the extracellular matrix (ECM) degradation during periodontitis." (PMID 33408824, 2020). "In the saliva of patients with periodontitis, increased concentrations of MMP-2, MMP-8 and MMP-9 were found in comparison to healthy patients." (PMID 33297580, 2020). "Biomarkers that decreased after scaling and root planning (SRP) and oral hygiene instruction (OHI) in periodontitis patients were IL-1β, MMP-8, MMP-9, prostaglandin E2 (PGE2), and TIMP-2." (PMID 33383828, 2020). "Other studies confirmed elevated levels of MMP9 in GCF and gingival tissue of periodontitis patients." (PMID 32867386, 2020). "When comparing chronic periodontitis patients with gingivitis patients and healthy control subjects, higher levels of MMP-8 in saliva and higher MMP-9 levels in gingival crevicular fluid (GCF) were detected." (PMID 32650590, 2020). "The biomarkers that decreased after SRP and OHI in periodontitis patients were IL-1β, MMP-8, MMP-9, PGE2, and TIMP-2." (PMID 33383828, 2020). "There seems to be a significant increase in MMP expression and activity in chronic periodontitis, especially MMP-1, MMP-3, MMP-7, MMP-8, and MMP-9, with minor contributions from MMP-13 and MMP-14." (PMID 32650590, 2020). "In spite of the difficulties, this study can be the start of a series of further studies that will confirm or deny the main role of both MMP-9 and MPO in the progression of chronic-inflammatory processes such as DM2 and periodontitis." (PMID 31355267, 2019). "Nevertheless, further investigation and randomized control trials are needed to confirm or discard the possible relationship between the elevation of MMP-9 and MPO levels in samples of patients with periodontitis and T2D." (PMID 31355267, 2019). "Immunohistochemical staining of TNF-α, IL-1β and MMP-9 in mandible sections yielded a much stronger staining intensity in gingiva and PDL area from periodontitis induced rats compared to control rats, but this was mitigated in PDT treated rats." (PMID 31160615, 2019). "It was reported that in periodontitis patients, MMP-13 induces pro-MMP-9 activation in gingival tissue." (PMID 31340803, 2019). "Consistent with previous studies, our results indicate that SHI down-regulates IL-1, IL-6, TNF-α, MMP-2, MMP-9 and COX-2 expression in LPS-stimulated hPDLCs, thus indicating the anti-inflammatory potential of SHI in the treatment of periodontitis." (PMID 30392422, 2018). "Ex vivo evidence from progressive chronic periodontitis in humans supports a role for MPO in direct activation of latent MMP-8 and MMP-9, and the inactivation of TIMP-1." (PMID 28218665, 2017). "MMP‐8, MMP‐9, and their metalloproteinase inhibitor‐1 (TIMP‐1) have been particularly investigated as periodontitis markers (Gorska & Nedzi‐Gora, 2006)." (PMID 29744196, 2017). "Cluster 4 contained 10 genes that were positively correlated with both MMP9 and CTSK in periodontitis." (PMID 27486459, 2016). "Cluster 3 was a subset with 14 genes that negatively correlated with MMP2 in healthy samples and positively correlated with MMP9, RANKL, and CTSK in only the periodontitis samples." (PMID 27486459, 2016).
periodontitis (continued). "Cluster 5 genes (n = 34) showed a positive correlation with MMP9, RANKL, and CTSK in both healthy and periodontitis tissues, and a positive correlation with TNFα, but only in the healthy tissues." (PMID 27486459, 2016). "It was found that the levels of MMP-8, MMP-9, OPG, and IL-1β declined significantly after treatment in volunteers with moderate to severe periodontitis." (PMID 24944840, 2014). "Our study also demonstrated that PTL suppressed MMP-9 gene expression and protein abundance, indicating the potential of PTL in preventing matrix degradation in periodontitis." (PMID 25610476, 2014). "The periodontium of untreated rats with experimental periodontitis showed marked immune-staining for COX-2, MMP-2, MMP-9, RANK-L, and RANK, compared to normal rats treated with saline alone." (PMID 24130702, 2013). "Carvedilol (10 mg/kg) treatment reduced the levels of COX-2, MMP-2, MMP-9, RANK-L, and RANK expression in the periodontium of rats subjected to experimental periodontitis." (PMID 23843954, 2013). "In periodontitis, it has been proposed that the relationship between ROS and MMPs is bidirectional; the increase in ROS activates latent MMPs, specifically collagenase MMP-8 and gelatinase MMP-9, which are directly responsible for collagen breakdown." (PMID 41590173, 2026). "On the contrary, there are periodontitis-negative bacterial strains within the OM, such as Corynebacterium matruchotti, that counteract MMP-9 elevation in oral host tissues." (PMID 40332093, 2025). "The determination of salivary MMP-9 levels in patients with periodontitis, with or without DM, shows values twice as high in the DM–periodontitis association compared to the group of patients with periodontitis alone." (PMID 40243433, 2025). "Furthermore, ELISA analysis of periodontitis-related markers in the blood showed that W. cibaria CMU exhibited significant preventive ability to induce periodontitis in TNF-α, IL-6, MMP-1, and MMP-9 categories." (PMID 40007939, 2025). "The strong interactions of EGCG with ESR1, MMP2, MMP9, MMP13, and STAT1 support its potential to modulate MMP activity and reduce extracellular matrix degradation, thereby mitigating tissue destruction in periodontitis." (PMID 41009706, 2025). "MMP-8, MMP-9, IL-1β, IL-6, and Hb have been effective salivary biomarkers for detecting periodontitis in systemically healthy individuals, while MMP-9 and IL-1β also perform well in identifying non-periodontitis conditions." (PMID 39554809, 2024). "We hypothesize that the supplementation with ω-3 PUFA, in ligature-induced periodontitis, could reduce periodontal destruction by decreasing inflammatory markers and with MMP-2 and MMP-9 activation as a mechanism of action." (PMID 37378834, 2024). "Other ways to arrest periodontitis could be achieved by MMP activity neutralization using recombinant TIMPs or antibodies directed against MMPs; it was shown that antibodies against MMP-9 and MMP-14 in combination significantly inhibited bone resorption." (PMID 38474009, 2024). "In another induced periodontitis in a diabetic rat experiment, Cu reduced the infiltration of PMN and monocytes, the degradation of periodontal collagen fibers—and decreased IL-1β, IL-6, TNF-α MMP-9 and MMP-2, MMP-8 levels." (PMID 38793109, 2024). "High concentrations of MMP-9 have been correlated with high gingival bleeding and intense dental motility and, together with MMP-2, it is responsible for a greater degradation of extracellular matrix constituents in periodontitis." (PMID 37026605, 2023). "Moreover, some promising biomarkers of periodontitis were suggested, such as matrix metalloproteinase-8 (MMP-8), matrix metalloproteinase-9 (MMP-9), interleukin 1 beta (IL1β), and interleukin 6 (IL6)." (PMID 37535199, 2023).
periodontitis (continued). "In conclusion, five hub cross-talk genes, i.e., CCL5, FCGR3B, MMP-9, SAA1, and SELL, could be involved in the interplay between periodontitis and CKF, whereby primarily inflammation, metabolic, and vascular issues appear to be of relevance." (PMID 37510279, 2023). "It was observed that the MMP-9 concentrations of the diabetic subjects with chronic periodontitis showed an almost two-fold increase compared to the non-diabetic subjects." (PMID 35408573, 2022). "The primary MMPs of chronic periodontitis are MMP-8 and MMP-9." (PMID 35408573, 2022). "Likewise, the ROC curve showed a statistically significant diagnostic accuracy (sensitivity and specificity) with an AUC of 1.000 (p value = 0.0001) for both the MMP-8/TIMP-1 and MMP-9/TIMP-1 combinations when comparing periodontal health and periodontitis S1." (PMID 36292174, 2022). "Interestingly, when using ratios, the diagnostic potential increased with MMP-8/TIMP-1 (AUC of 0.986, p value = 0.0001) and MMP-9/TIMP-1 (AUC of 1.000, p value = 0.0001) between periodontal health and periodontitis." (PMID 36292174, 2022). "Hence, the research identified the fact that MMP-8, MMP-9, and MMP-2 biomarkers can aid in the diagnosis of periodontitis." (PMID 35626325, 2022). "However, when comparing the ratios of MMP-8/TIMP-1 and MMP-9/TIMP-1, the results showed significant differences in all periodontitis groups in comparison to the control group." (PMID 36292174, 2022). "Similarly, these cut-off points of both MMP-8/TIMP-1 and MMP-9/TIMP-1 combinations showed the highest sensitivity and specificity (1.000 each) for differentiation between control and S1 periodontitis." (PMID 36292174, 2022). "MMP-3 (stromelysin-1) is a notable proteolytic enzyme among the other MMP types due to its central role in activating the latent MMP types such as MMP-7, MMP-8, MMP-9, and MMP-13, and it has been claimed that MMP-3 has a pivotal function in the initiation of collagen disintegration in periodontitis." (PMID 34684209, 2021). "Thus, we propose the use of MMP-9 and especially MMP-8 levels as biomarkers of periodontal disease during orthodontic treatment to facilitate the detection of early periodontitis or gingivitis." (PMID 33567492, 2021). "The plotted ROC curves showed a good predictor value for the MMP-9/TIMP-1 ratio, the (MMP-8 + MMP-9)/TIMP-1 ratio and the MMP-8 + MMP-9 sum (as top three), followed by the MMP-8/TIMP-1 ratio, HGF, MMP-2, and OPG for differentiation of periodontitis versus gingivitis conditions (AUC ≥ 0.85)." (PMID 33742017, 2021). "Considering that gingival tissues-derived MMP-3 contributes to the progression of adult periodontitis by activating MMP-8 and MMP-9 derived from crevicular fluid neutrophil, increased expression of MMPs would be responsible for age-related periodontal inflammation." (PMID 33477537, 2021). "In addition, matrix metalloproteinase-8 (MMP-8), matrix metalloproteinase-9 (MMP-9), and matrix metalloproteinase-13 (MMP-13) are present in higher levels in the saliva of individuals with periodontitis than in the saliva of healthy individuals." (PMID 35048079, 2021). "Therefore, based on this evidence, this study aimed to evaluate the serum and salivary levels of MMP-9 in patients with periodontitis and with CVD, and to investigate the effect of periodontitis and CVD on serum and salivary levels of MMP-9." (PMID 33810003, 2021). "MMP-9 concentrations in serum and saliva were statistically elevated in patients with CVD (p < 0.01) and in patients with periodontitis plus CVD (p < 0.001) compared to patients with periodontitis and healthy subjects." (PMID 33810003, 2021). "IL-1β activates generation of matrix metalloproteinase (MMP)-9 in periodontitis and promotes the expression of the receptor activator of nuclear factor kappa-B ligand (RANKL), contributing to osteoclastogenesis in periodontitis." (PMID 32328131, 2020).
periodontitis (continued). "Matrix metallopeptidase-9 (MMP-9), which is known to be able to detect the progression of periodontitis in general, was not significantly different between OVX and Sham groups." (PMID 30246792, 2018). "Cluster 8 genes (n = 18) were similar to cluster 7 with negative correlations to MMP2 and CTSK in periodontitis and health, as well as negative correlations with MMP9 in periodontitis tissues." (PMID 27486459, 2016). "Cluster 1 contained 15 genes showing a positive correlation with TNFα and negative correlation with MMP9, primarily in the periodontitis tissues." (PMID 27486459, 2016). "Salivary MMP-8 (but not MMP-9) levels were found to be reduced after nonsurgical treatment for periodontitis in 33 patients but, interestingly, not if adjunctive doxycycline treatment was included." (PMID 24944840, 2014). "Multiple neutrophil-derived proteolytic enzymes have been shown to be elevated in periodontitis compared to healthy controls, including myeloperoxidase (GCF) and matrix metalloproteinases (e.g., MMP-2 and MMP-9) whose major source in the periodontium is the neutrophil." (PMID 23843954, 2013). "Furthermore, the periodontium of rats with periodontitis and treated with a high-dose of Atorvastatin had even lower levels of COX-2, as well as MMP-2, MMP-9, RANK-L and RANK." (PMID 24130702, 2013). "Previous works support that MMP -2, MMP-9 and MMP-13 play important roles in both, the initiation and progression of inflammatory bone resorption and soft periodontal tissue breakdown during pathological processes, including chronic periodontitis." (PMID 22436166, 2012). "Similarly, MMP9 levels were found to be abundant in GCF, with baseline concentrations measured at 165.79 ng/mL in healthy sites, 222.01 ng/mL in gingivitis sites, and 331.56 ng/mL in periodontitis sites." (PMID 41303313, 2025). "Therefore, the link between SSc and periodontitis or its severity levels, in the context of the higher MMP-9 levels in SSc subgingival biofilm samples, is not possible using these findings." (PMID 38779873, 2024). "According to our model, rosacea (but not periodontitis, tobacco smoking, and age) could be responsible for 32% of the increased level of MMP-9 in the GCF." (PMID 36077255, 2022). "Among MMP members, MMP-8 and MMP-9 were found to be elevated in the blood of patients with type 2 diabetes and metabolic syndrome, and higher concentrations of MMP-8 and−9 have been reported in the gingival tissues and oral fluids of diabetic patients with periodontitis." (PMID 35757444, 2022). "Moreover, it was noticed that the expression and activity of MMP-9 were increased in experimental periodontitis, regardless of the method of periodontitis induction." (PMID 33746772, 2021). "The plotted ROC curves showed a good predictor value of the MMP-9/TIMP-1 ratio, (MMP-8 + MMP-9)/TIMP-1 ratio, and HGF (as top three), followed by the MMP-9, MMP-2, MMP-8 + MMP-9 sum and the MMP-8/TIMP-1 ratio, for differentiation of periodontitis versus health conditions (AUC ≥ 0.95)." (PMID 33742017, 2021). "In addition, the expression of MMP-9 and MMP-13 could be relevant predictive indicators for the progression of periodontitis." (PMID 33294463, 2020). "Gelatinase (MMP-9) degrades collagen intercellular ground substance and may serve as a guide in periodontal treatment monitoring as its level is higher in GCF of the patients with chronic periodontitis than in healthy patients." (PMID 24490073, 2013). "In addition, MMP-9 was shown to be a sensitive marker for periodontal inflammation during orthodontic treatment, and VEGF-A, which belongs to the vascular endothelial growth factor (VEGF) family, plays an important role during the pathological process of periodontitis." (PMID 40004956, 2025).
periodontitis (continued). "A negative association was reported between MMP-9 and Fusobacterium nucleatum, Porphyromonas gingivalis, Tannerella forsythia, Prevotella intermedia, and Prevotella nigrescens, in GCF in individuals with chronic periodontitis, suggesting an anti-inflammatory effect of MMP-9 in periodontitis." (PMID 36077255, 2022). "Chlorhexidine, the most widely used adjuvant in the treatment of periodontitis, acts as a non-specific MMPI through chelation of calcium and zinc cations, inhibiting MMP-2, MMP-8, and MMP-9." (PMID 41002732, 2025). "In a recent study of the oral cavity of SSc patients, the expression of MMP-9 and CXCL4, but not IL-6, in the GCF correlated with early-stage SSc and several parameters of periodontitis." (PMID 38779873, 2024). "The diagnosis of rosacea was responsible for the levels of MMP-9 in the GCF (p < 0.05), as opposed to periodontitis, smoking, and age (p > 0.05)." (PMID 36077255, 2022). "This study evaluated the gene expression of IL-1ß, IL-6, TNF-α, MMP-1, MMP-2, MMP-8, MMP-9, TIMP-1, and TIMP-2 in the gingival tissue of individuals with periodontitis or peri-implantitis compared to individuals without periodontal or peri-implant disease." (PMID 33291232, 2020). "We investigated serum and saliva concentrations of matrix metalloproteinases, MMP‐8, MMP‐9, and MMP‐13, and their tissue inhibitor TIMP‐1, in a group of patients with and without periodontitis from Sweden." (PMID 29744196, 2017). "In serum, the MMP‐8, MMP‐9, and TIMP‐1 concentrations were slightly higher in the no‐periodontitis patients but the differences were not statistically significant." (PMID 29744196, 2017). "In saliva, MMP‐8, MMP‐9, and TIMP‐1 values were slightly higher in the periodontitis patients, but again, the differences between groups were not significant." (PMID 29744196, 2017). "Cluster 6 contained 34 genes with strong positive correlations with MMP9 and CTSK in both healthy and periodontitis tissues, and a negative correlation with TNFα in periodontitis." (PMID 27486459, 2016). "The periodontium of rats presenting with experimental periodontitis receiving no treatment (EPD) showed marked immune-staining for to the following markers: MMP-2, MMP-9, COX-2, RANK-L, and RANK compared to periodontium staining profile of the saline group." (PMID 23843954, 2013). "However, Gonçalves and colleagues revealed that MMP transcripts (for MMP-1, MMP-2, MMP-9, and MMP-13) found in gingiva samples were not significantly different in patients affected by gingivitis, chronic periodontitis, and aggressive periodontitis." (PMID 38474009, 2024). "The results showed significant differences in the detection of P. gingivalis (p < 0.001), P. intermedia (p < 0.01), P. nigrescens (p < 0.001) and T. forsythia (p < 0.001), but also in the levels of MMP-8 and MMP-9 in GCF between patients with and without periodontitis." (PMID 35448062, 2022). "However, SDD (20 mg twice daily) circumvents these issues—sustaining MMP-9 suppression via non-bactericidal mechanisms, with an FDA-approved indication for chronic use in periodontitis and rosacea and a long-standing record of microbiologic safety and systemic tolerability." (PMID 41304763, 2025).